GBE1 (1,4-alpha-glucan branching enzyme 1)
Diseases named in the same sentence as GBE1 in open-access papers (continued):
Sharing a sentence is not in itself a finding about the gene and the disease.
melanoma (4 papers, 2017 to 2022). A malignant, usually aggressive tumor composed of atypical, neoplastic melanocytes. "Additionally, GBE1 levels are associated with the efficacy of anti-PD1 treatment in melanoma patients." (PMID 32439898, 2020). "Previous study indicated that GBE1 expression was upregulated in acute myelocytic leukemia and the level of GBE1 was associated with the efficacy of anti-PD1 treatment in melanoma patients." (PMID 35155189, 2021). "We identified a gene expression signature, and discuss the putative prognostic and predictive potential of BNIP3 and GBE1 genes in the clinical outcome of melanoma patients treated with anti-PD1 (pembrolizumab)." (PMID 29312568, 2017). "We could demonstrate that the levels of BNIP3 and GBE1 correlate with the clinical response in melanoma patients treated with anti-PD1." (PMID 29312568, 2017).
ovarian carcinoma (4 papers, 2009 to 2024). A malignant neoplasm originating from the surface ovarian epithelium. "On the other hand, GBE1 expression is decreased in ovarian cancer, and GBE1 downregulation is correlated with poor clinical outcomes." (PMID 36900384, 2023). "GBE1, which plays a role in carbohydrate metabolism, has been found to be down regulated in ovarian cancers." (PMID 19911042, 2009). "RT-PCR analyses of ovarian cancer samples validated gene expression profiles of TMEM158, GBE1 and HEG1 from a chromosome 3 transcriptome analysis and IGFBP4, PTRF and C1QTNF1 from a chromosome 17 transcriptome analysis." (PMID 19580657, 2009).
hydrops fetalis (3 papers, 2020 to 2022). Hydrops fetalis is a severe and challenging fetal condition usually defined as the excessive accumulation of fetal fluid within the fetal extravascular compartments and body cavities that manifests as edema, pleural and pericardial effusion and ascites. "Case 90759, a 13-week fetus with hydrops fetalis observed in ultrasonography, was found to have two heterozygous variants in GBE1 gene (trans): c.467G > A and c.-35_-54del GCTCAGGCCCCACTCGACCC." (PMID 33772059, 2021). "Few studies have been performed using GBE1-knockout mice because of the occurrence of hydrops fetalis resulting from glycogen storage disease type IV35." (PMID 32439898, 2020).
hepatic disease (2 papers, 2024 to 2025). "Predicting hepatic disease severity based on GBE1 genotype is challenging because of the rarity of this disorder and the high prevalence of private mutations, which complicates the effort to infer robust genotype-phenotype relationships." (PMID 38912588, 2024). "The statistically significant increase in GBE1 expression in HLCs derived from WJ-MSCs could lead to possible therapeutic use for treating these specific hepatic diseases." (PMID 40001892, 2025). "Despite not being able to elucidate clear genotype-phenotype relationships, the genotype data from our cohort suggest that a less severe hepatic disease course (i.e., intermediate progressive or attenuated) does not occur in individuals with 2 null GBE1 variants." (PMID 38912588, 2024).
pancreatic cancer (2 papers, 2024 to 2025). "Glucan branching enzyme 1 (GBE1), which is involved in cellular glycogen metabolism, is upregulated in pancreatic cancer and is associated with poor prognosis." (PMID 40448344, 2025). "Overexpression of GBE1 promotes the proliferation of pancreatic cancer cells, whereas knockdown of GBE1 alleviates the malignant phenotype." (PMID 40448344, 2025). "The potential function of GBE1 in pancreatic cancer progression have not been elucidated." (PMID 38961325, 2024).
carbohydrate metabolic disorder (1 paper, 2024). "ASL, AGL and GBE1 are among 135 genes revealed to be co-expressed in carbohydrate metabolic disorder." (PMID 38592052, 2024).
cervical cancer (1 paper, 2017). A primary or metastatic malignant neoplasm involving the cervix. "Deletion of 3p12.1 (GBE1) has been associated with prognosis in cervical cancer, but not in ESCC previously." (PMID 27974698, 2017).
Failure to thrive (1 paper, 2017). Failure to thrive (FTT) refers to a child whose physical growth is substantially below the norm. "In the U.S. Quarter Horse population, phenotypes created by homozygotes for GBE1 mutations ranged from stillbirth to early failure to thrive, with death never occurring later than 18 weeks of age." (PMID 29047335, 2017).
glioma (1 paper, 2023). A benign or malignant brain and spinal cord tumor that arises from glial cells (astrocytes, oligodendrocytes, ependymal cells). "To further verify the alteration of the metabolic pattern of glioma cells caused by GBE1 knockdown, we performed oxygen deprivation assays in U87 and U251 cells." (PMID 36900384, 2023). "The inhibition of glioma caused by GBE1 knockdown was reversed." (PMID 36900384, 2023). "Bioinformatics analysis showed a strong association of GBE1 with glioma." (PMID 36900384, 2023). "However, the knockdown of FBP1 reversed the inhibition of glycolysis caused by GBE1 knockdown, indicating that the increased expression of FBP1 is an important reason for the impaired glycolysis of glioma cells caused by GBE1 knockdown." (PMID 36900384, 2023). "The mRNA expression profiles and clinical information of 584 glioma samples from the TCGA database and 686 glioma samples from the CGGA database revealed a significant positive correlation between GBE1 expression and WHO grade of gliomas." (PMID 36900384, 2023). "In glioma, we also observed that knockdown of GBE1 significantly inhibited the phosphorylation level of p65 protein, accompanied by elevated FBP1 expression." (PMID 36900384, 2023). "In vitro, we found increased apoptosis, arrested cell cycle, and suppressed cell proliferation in glioma cells with GBE1 knockdown." (PMID 36900384, 2023). "Herein, we evaluated GBE1’s role in gliomas, confirming that the expression of GBE1 is elevated in gliomas and correlates with a poor prognosis." (PMID 36900384, 2023). "GBE1 is involved in multiple biological behaviors of glioma cells, including migration, invasion, colony formation, and promotion of angiogenesis, and knockdown of GBE1 will impair these biological behaviors." (PMID 36900384, 2023). "GBE1 knockdown glioma cells in a hypoxic environment exhibit a malfunction in converting oxidative phosphorylation to glycolysis and a decreased tolerance to a hypoxic environment." (PMID 36900384, 2023). "Our study reveals a role for glycogen branching enzyme 1 (GBE1) in regulating glioma initiation and progression." (PMID 36900384, 2023). "Further studies revealed that glioma cells with knockdowns of both GBE1 and FBP1 showed a significant rebound in migration, invasion, vascularization, and colony formation ability compared with single GBE1 knockdowns." (PMID 36900384, 2023). "In vitro experiments showed that GBE1 knockdown slows glioma cell proliferation, inhibits multiple biological behaviors, and alters glioma cell glycolytic capacity." (PMID 36900384, 2023). "Our study found that GBE1 expression was significantly elevated in gliomas and was correlated with a poor prognosis." (PMID 36900384, 2023). "Further, we subdivided the glioma samples according to IDH mutation status and 1p/19q deletion status and found higher GBE1 expression in IDH wild-type gliomas compared to IDH mutant ones." (PMID 36900384, 2023). "In contrast, knockdown of the elevated FBP1 based on GBE1 knockdown restored glioma cell proliferation and impaired tumor biological behavior." (PMID 36900384, 2023). "Its area under the curve (AUC) was 89.15% compared to 74.21% of KI67, indicating that GBE1 can be considered a discriminator of glioma malignancy." (PMID 36900384, 2023). "GBE1 downregulates FBP1 expression through the NF-κB pathway, causing a shift in the glucose metabolism pattern of glioma cells to glycolysis, enhancing the Warburg effect, and promoting the development of glioma." (PMID 36900384, 2023). "We determined by bioinformatics analysis that GBE1 expression is elevated in gliomas and correlates with poor prognoses." (PMID 36900384, 2023). "The results showed that GBE1 knockdown increased the basal respiration level and spare respiration capacity of mitochondria in both glioma cell lines." (PMID 36900384, 2023).
glioma (continued). "Compared to the negative control, the expression of cyclin D1 was significantly reduced after GBE1 knockdown, which further proved that GBE1 knockdown could transform glioma cells into a resting state and inhibit proliferation." (PMID 36900384, 2023). "Furthermore, the results of IHC staining of tumor tissues and adjacent normal tissues from three glioma patients confirmed the higher expression of GBE1 in glioma samples." (PMID 36900384, 2023). "Additionally, GBE1 knockdown also affected glioma cell migration, invasion, colony formation, and angiogenesis abilities." (PMID 36900384, 2023). "Our study found elevated expression of GBE1 in gliomas and a correlation with a poor prognosis." (PMID 36900384, 2023). "We found that the expression of GBE1 correlated with a poor prognosis in glioma patients." (PMID 36900384, 2023). "Our results showed that the NF-κB pathway was inhibited following GBE1 knockdown in glioma cells, accompanied by elevated FBP1 expression; this paralleled the effects of single NF-κB pathway inhibitors, suggesting that regulation of FBP1 expression by GBE1 via NF-κB is also applicable in glioma." (PMID 36900384, 2023). "Subsequently, we evaluated the performance of GBE1 in distinguishing glioma grades by ROC curve." (PMID 36900384, 2023). "Furthermore, our findings validated the mechanism by which GBE1 affects glucose metabolism patterns for the first time in glioma." (PMID 36900384, 2023). "Furthermore, the results of apoptosis analysis showed that GBE1 knockdown induced apoptosis in all three glioma cell lines." (PMID 36900384, 2023). "To investigate whether GBE1 knockdown has additional effects on glioma, we assessed the alterations of glioma cells in biological behaviors such as migration, invasion, colony formation, and angiogenesis after GBE1 knockdown." (PMID 36900384, 2023). "Therefore, we analyzed TCGA and CGGA data and found that GBE1 expression was elevated in gliomas and correlated with a poor prognosis." (PMID 36900384, 2023). "And FBP1 levels were significantly elevated after QNZ treatment compared to vehicle control, which paralleled the effect of GBE1 knockdown, indicating that the conclusion that GBE1 regulates FBP1 expression through the NF-κB pathway is also applicable in gliomas." (PMID 36900384, 2023). "Furthermore, GBE1 was more reliable than KI67 in predicting glioma grade." (PMID 36900384, 2023). "We then demonstrated through cellular and animal experiments that GBE1 influences FBP1 expression through the NF-κB pathway, which affects the glucose metabolism pattern of glioma cells and promotes the Warburg effect to drive tumor progression." (PMID 36900384, 2023). "Our study confirmed that in glioma cells, FBP1 expression was significantly elevated after GBE1 knockdown." (PMID 36900384, 2023). "Given that previous results showed GBE1 negatively regulated FBP1 expression in U251 cells, to further verify the role of FBP1 in gliomas, we constructed U251 cells with FBP1 knockdown (sh-FBP1) and FBP1 overexpression (oe-FBP1)." (PMID 36900384, 2023). "The immunofluorescence staining of KI67 showed that after GBE1 knockdown, the resting cells with low KI67 expression in all three glioma cell lines increased significantly, which was consistent with the results of cell cycle analysis." (PMID 36900384, 2023). "The results showed that the proliferation of all three glioma cell lines was inhibited in the GBE1 knockdown group compared with the negative control." (PMID 36900384, 2023). "Collectively, GBE1 reduces FBP1 expression through the NF-κB pathway, shifting the glucose metabolism pattern of glioma cells to glycolysis and enhancing the Warburg effect to drive glioma progression." (PMID 36900384, 2023). "Moreover, GBE1 promotes glioma progression by enhancing aerobic glycolysis through the inhibition of fructose–bisphosphatase 1 (FBP1), which reveals GBE1 as a potential target for glioma therapy." (PMID 36900384, 2023).
glioma (continued). "Furthermore, the colony formation assay results showed that the colony formation ratios of all three glioma cell lines decreased significantly after GBE1 knockdown compared to the negative control." (PMID 36900384, 2023). "To investigate whether GBE1 regulates glioma progression through FBP1, we constructed U87 and U251 cell lines in which both GBE1 and FBP1 were knocked down and observed whether the inhibition of glioma by single GBE1 knockdown could be reversed." (PMID 36900384, 2023). "To further investigate why FBP1 inhibited glioma progression, considering the important role of FBP1 in glucose metabolism, we speculated that the glucose metabolic system of glioma cells was affected after GBE1 knockdown, which in turn inhibited glioma progression." (PMID 36900384, 2023). "However, there has not been enough significant research on GBE1 in gliomas." (PMID 36900384, 2023). "Moreover, real-time recorded images of the tube formation assay showed that conditioned medium (CdM) from GBE1 knockdown glioma cells made HUVECs form fewer tubules compared with the negative control, indicating that GBE1 knockdown impaired the ability of glioma cells to promote angiogenesis." (PMID 36900384, 2023).
memory impairment (1 paper, 2022). "Using exome sequencing, we identified two previously unreported bi-allelic missense GBE1 variants in a patient with severe memory impairment along with the typical non-cognitive symptoms." (PMID 34999962, 2022).
metabolic myopathy (1 paper, 2021). A group of rare inherited disorders characterized by a deficiency of enzymes that are involved in metabolic pathways that affect muscles. "Finally, seven proteins were associated with metabolic myopathy where Cacna1s, Ampd1, Pygm, Gys1, and Pfkm were upregulated and where Gbe1 and Ca2 were downregulated." (PMID 34828261, 2021).
Mitochondrial myopathy (1 paper, 2025). "In metabolic or mitochondrial myopathy, 2 of 8 patients (25%) carried variants in GAA (n = 1) and GBE1 (n = 1)." (PMID 40494860, 2025).
Rb (1 paper, 2019). "This is the first study suggesting that these genes, FGFR4, NQO1, ACADS CX3CR1, GBE1, KRT85, and TYR genes, may play a role in the etiology of Rb." (PMID 31207142, 2019).
Stroke (1 paper, 2014). Sudden impairment of blood flow to a part of the brain due to occlusion or rupture of an artery to the brain. "Real-Time RT-PCR data revealed that mRNA expression levels of Gbe1, Gys1, and Pygb remained unchanged in contralateral and ipsilateral hemispheres of both sham and stroke rat brains at 6 and 24 hours time points (n = 5)." (PMID 24858129, 2014). "To assess whether ischemic insult alters the mRNA expression level of genes involved in glycogen metabolism we measured mRNA expression level of Gbe1, Gys1, Agl and Pygb in the contralateral and ipsilateral hemispheres of sham and stroke-affected rat brains." (PMID 24858129, 2014).
type 2 diabetes (1 paper, 2024). "mRNAs for LDHA, PDK1 and GBE1 were induced to a similar degree in myotubes from donors with NGT or type 2 diabetes." (PMID 38814443, 2024). "HIF target gene mRNAs for LDHA (encoding lactate dehydrogenase A), PDK1 (encoding pyruvate dehydrogenase kinase isoform 1) and GBE1 (encoding glycogen-branching enzyme 1) were induced similarly in response to roxadustat in myotubes when comparing the NGT and type 2 diabetes groups." (PMID 38814443, 2024).
Urinary incontinence (1 paper, 2017). Loss of the ability to control the urinary bladder leading to involuntary urination. "Mutations in GBE1 have been detected in patients of adult polyglucosan body disease with symptoms such as progressive gait difficulty, urinary incontinence, and reduced reflexes in lower limbs." (PMID 27188386, 2017).
von Hippel-Lindau disease (1 paper, 2022). An autosomal dominant disorder caused by pathogenic variants in the VHL gene, leading to an increased risk of various benign and malignant tumors, including hemangioblastomas, retinal hemangiomas, endolymphatic sac tumors, renal cell carcinoma, and pheochromocytomas.